RBM4 (RNA binding motif protein 4)
Diseases named in the same sentence as RBM4 in open-access papers (continued):
Sharing a sentence is not in itself a finding about the gene and the disease.
tumor (21 papers, 2015 to 2025). "To delineate the functional role of RBM4 in the tumor microenvironment, we performed gain and loss of function experiments." (PMID 38548747, 2024). "Three tumor-associated candidates (RBM4, GOLGA4 and UBQLN1) were selected to validate the RNA-seq data." (PMID 37415951, 2023). "Analysis of the network database revealed that RBM4 expression was significantly lower in ccRCC tissues than in non-tumor tissues." (PMID 39865075, 2025). "Conversely, the ability of TPM3P9 to promote ccRCC cell proliferation and tumor growth was markedly suppressed by overexpression of RBM4." (PMID 39865075, 2025). "Then we conducted rescue experiments on tumor cells that had knocked out circGRAMD4, RBM4 and NBR1 by knocking out B2M again to reduce the expression level of MHC-I on the cell surface." (PMID 40373256, 2025). "Collectively, these data suggest that TPM3P9 exerts its pro-tumor effect by modulating RBM4-mediated RNA splicing." (PMID 39865075, 2025). "Tumor cells were cotransfected with si-RBM4/RBM4-OE and SEMA7A-WT/5NQ and were then subjected to a CCK8 assay." (PMID 38548747, 2024). "As a splicing inhibitor, RBM4 regulates tumor-related splicing to perform the functions of tumor suppressor." (PMID 37415951, 2023). "To validate the role of RBM4 in regulating senescence in vivo, we carried out an immunohistochemistry (IHC) analysis using removed mice tumor samples." (PMID 36639375, 2023). "Our study therefore uncovered a novel tumor-promoting function of RBM4 in ESCC, offering a new potential biomarker for glutamine-dependent therapeutics." (PMID 37080995, 2023). "Surprisingly, RBM4, a known tumor-suppressive RBP in multiple cancers, was one of the top hits that was dramatically elevated in ESCC samples as compared to normal tissues." (PMID 37080995, 2023). "Compared with adjacent normal tissues, the relative protein levels of AURKA and RBM4-S were evidently increased in tumor tissues, while the relative protein levels of RBM4-FL were evidently decreased in tumor tissues." (PMID 35361747, 2022). "AURKA interferes with the YTHDC1-SRSF3 complex, thus inhibiting the production of tumor-suppressing isoform RBM4-FL." (PMID 35361747, 2022). "Collectively, we identify a new cancer-specific splicing event and discover that RBM4-S antagonizes the function of RBM4-FL to promote tumor progression." (PMID 35361747, 2022). "Consistently, we further verified the opposite functions of the two RBM4 isoforms on tumor growth in vivo." (PMID 35361747, 2022). "In summary, our work identifies m6A reader YTHDC1 as the fulcrum of tumor suppressor RBM4 oncogenic switch and reveals a previously unappreciated role of nuclear AURKA in regulating RNA splicing." (PMID 35361747, 2022). "Altogether, these results demonstrate that RBM4-S plays an opposite role as compared to the canonical tumor suppressor RBM4-FL, therefore, the splicing switch towards RBM4-S is partially responsible for AURKA-regulated tumor growth." (PMID 35361747, 2022). "Collectively, these results indicate that RBM4-S functions as a tumor promoter by abolishing RBM4-FL-mediated inhibition of SRSF1-mTORC1 signaling pathway activity." (PMID 35361747, 2022). "Previous studies showed that RBM4 was reduced in GC cells and it suppressed the growth and metastasis of GC tumor." (PMID 34195294, 2021). "As a positive control, RBM4 also inhibited tumour development in vivo, consistent with its role as antitumour splicing factor to promote TEAD-S." (PMID 27291620, 2016). "We generated H157 cells with stable expression of YAP, YAP/TEAD4-FL, YAP/TEAD4-S or YAP/RBM4, and injected these cells subcutaneously into the flanks of nude mice to measure tumour growth." (PMID 27291620, 2016). "RBM4 is a general splicing factor that functions as a tumour suppressor in a number of human cancers." (PMID 27291620, 2016).
tumor (continued). "For example, the splicing factor SRSF1 is found to act as a proto-oncogene to promote cell transformation, whereas the splicing suppressor RBM4 functions as a tumor suppressor to inhibit tumor progression." (PMID 25749525, 2015). "Taking the results together, RBM4 functioned as a tumor suppressor in reducing the progression and Warburg effect of CRC cells by reprogramming the CRC-associated splicing cascade." (PMID 26506517, 2015). "Most interesting, in light of our findings, was the finding based on RNA-Seq analysis that RBM4 expression promoted a tumor-suppressive splicing profile." (PMID 26565589, 2015). "Our data suggest that RBM4 further promotes tumor suppression by favoring the canonical splicing of ULBP1 mRNA, marking cells for elimination by the immune system." (PMID 26565589, 2015). "We then investigated whether RBM4 affects the immunosuppressive impact exerted by tumor cells on CD8+ T cells." (PMID 40373256, 2025). "Furthermore, in vitro CCK8 and wound healing assays combined with in vivo subcutaneous tumor formation assay showed that overexpressing RBM4-FL repressed, whereas RBM4-S enhanced, the proliferation and migration of breast cancer cells." (PMID 37415951, 2023). "We next determined whether the senescence induced by RBM4-depletion played crucial roles in tumor suppression." (PMID 36639375, 2023). "Opposite to RBM4-FL, RBM4-S significantly promotes tumor growth both in vitro and in vivo." (PMID 35361747, 2022). "Similarly, RBM4 was shown to suppress tumor progression and to counter a colorectal metastatic cascade through modulation of alternative splicing, and its expression was decreased in various tumor types." (PMID 30618566, 2018). "We speculate that tumor cells are under selective pressure to downregulate RBM4 expression, as this would allow tumors to evade tumor-suppressive events such as expression of Bcl-xS and ULBP1." (PMID 26565589, 2015). "Moreover, RBM4 influenced the utilization of the 5′ss of Bcl-x, an apoptosis regulator, inducing a shift from the anti-apoptotic isoform (Bcl-xL) to the pro-apoptotic isoform (Bcl-xS), thereby promoting apoptosis and impeding tumor progression." (PMID 37875914, 2023). "The results of Co-IP and western blot analysis of tumor samples from the in vivo model confirmed the interaction between TPM3P9 and RBM4, and showed that TPM3P9 upregulated the expression of TCF7L2-L, an effect that was abolished by RBM4 overexpression." (PMID 39865075, 2025). "We also collected fresh-frozen tumor and the corresponding normal tissue specimens from ESCC patients and examined the protein levels of RBM4 and LKB1." (PMID 37080995, 2023). "To this end, we measured the protein expression of RBM4 and LKB1 on human ESCC tissue microarrays containing 192 tumor tissue and adjacent normal tissue samples by immunohistochemistry staining." (PMID 37080995, 2023). "Concerning the relative mRNA levels, tumor tissue manifested higher AURKA and RBM4-S but lower RBM4-FL than adjacent normal tissue." (PMID 37415951, 2023). "The results indicated that the expression levels of these four SFs, including NOVA1, RBM4, HNRNPC, and HNRPLL, in tumor tissues were significantly decreased, compared to those in normal tissues." (PMID 35832652, 2022). "Co-expression of YAP/TEAD4-FL strongly induced EMT in two primary tumour cell lines as judged by increased levels of N-cadherin and Vimentin; however, the expression of TEAD4-S or RBM4 suppressed the induction of EMT markers." (PMID 27291620, 2016). "Together, RBM4 is notably increased in ESCC in independent patient cohorts, suggesting that RBM4 might function as a tumor-promoting RBP in ESCC." (PMID 37080995, 2023). "Consistently, RBM4 and TEAD4-S inhibit tumour progression in cultured cells and xenograft tumours." (PMID 27291620, 2016).
tumor (continued). "Using TMAs, we analyzed RBM4 protein expression in 813 (94.4%) of the 861 samples in the TMA, The remaining samples were lost during antigen retrieval or there were no tumor tissues found in the core." (PMID 27324405, 2016). "Although the role of other members of the RBM proteins family in tumor treatment and prognosis is not clear, existing studies have shown that some members of RBM proteins family, such as RBM3, RBM4, and RBM39, play an essential role in tumor treatment and prognostic markers." (PMID 34804951, 2021).
infection (2 papers, 2020 to 2024). The state of being infected such as from the introduction of a foreign agent such as serum, vaccine, antigenic substance or organism. "Our collective findings point to pervasive and consistent RNA splicing changes, partly mediated by Lark/RBM4, as being an important aspect of the gut response to infection." (PMID 31948480, 2020).
neurodevelopmental disorder (1 paper, 2023). A behavioral and cognitive disorder with onset during the developmental period that involves impaired or aberrant development of intellectual, motor, or social functions. "Although RBM4 is not yet known to be linked to any neurodevelopmental disorders, our result that chronic treatment with 7,8-DHF improved motor learning in young Rbm4dKO adults provides a means to correct behavioral abnormalities associated with BDNF deficiency." (PMID 37670183, 2023).
RBM4 also shares sentences with these, for which no sentence is quoted: colorectal cancer (3 papers); ovarian carcinoma (2); cervical cancer (1); chronic myelogenous leukemia (1); colon cancer (1); hereditary leiomyomatosis (1); insomnia (1); intraepithelial neoplasia (1); joint effusion (1); signet ring cell carcinoma (1).